KDM5B (lysine demethylase 5B)
Diseases named in the same sentence as KDM5B in open-access papers (continued):
Sharing a sentence is not in itself a finding about the gene and the disease.
cancer (continued). "KDM5B (also known as JARID1B/PLU-1) has also been identified as being highly elevated in lung tumor tissues compared with corresponding non-neoplastic tissues and siRNA knockdown of KDM5B significantly suppressed the proliferation of cancer cells and increased the number of cells in sub-G1 phase." (PMID 24212667, 2011). "Quantitative analysis shows that the KDM5B-NTT/PLU-1 ratio varies between 0.2 and 0.7 without a clear correlation with the cancer subtype classification." (PMID 36697763, 2023). "The ratio between the canonical isoform PLU-1 and KDM5B-NTT is variable in the different cell lines without a clear correlation with the cancer subtype classification." (PMID 36697763, 2023). "In cancer cells, KDM5B regulates the expression of oncogenes and tumor suppressors by modulating H3K4 methylation levels, but the functions and mechanisms of KDM5B are not clear in EwS." (PMID 35428764, 2022). "Unlike KDM5B, REXO4 is much less well-investigated in cancer biology." (PMID 35954332, 2022).
infection (9 papers, 2015 to 2024). The state of being infected such as from the introduction of a foreign agent such as serum, vaccine, antigenic substance or organism. "Inhibition of KDM5B has also been shown to increase the expression of ISGs and potentiate resistance to infection by both DNA and RNA viruses." (PMID 32117236, 2020). "On the other hand, it has been shown that suppression of the KDM5B gene product, a H3K4 demethylase causing transcriptional repression, results in increased expression of IFN-β and other inflammatory cytokines following infection with respiratory syncytial virus (RSV)." (PMID 29253856, 2017). "Another small molecule inhibitor of KDM5B, the inhibitor GS‐5801, was found to inhibit HBV viral activity in a model of primary human hepatocyte infection." (PMID 39643939, 2024).
neurodevelopmental disorder (7 papers, 2020 to 2026). A behavioral and cognitive disorder with onset during the developmental period that involves impaired or aberrant development of intellectual, motor, or social functions. "Accordingly, we attributed the Chiari malformation to the variant in KDM5B whereas the one in BCORL1 was presumably responsible for the mild neurodevelopmental disorder of both kids, as reported in Shukla–Vernon syndrome (#301029)." (PMID 33337535, 2021). "In contrast, genes downregulated in SMS cortical neurons are involved in anatomical structure and multicellular organism development, including genes implicated in neurodevelopmental disorders (i.e., CHD4, UBE3B, KDM5B, and SETD1B)." (PMID 40882620, 2025). "This study extends our understanding of the KDM5B-related neurodevelopmental disorder and suggests the pathogenicity of certain dominant KDM5B missense variants." (PMID 39202393, 2024). "It is worth noting that genes encoding other members of the KDM5 family, KDM5B and KDM5C, are disrupted in neurodevelopmental disorders." (PMID 33350388, 2020). "A recent report of a patient with a developmental disorder and a duplication involving four genes, including KDM5B, suggested that KDM5B hyperactivity might disrupt the expression of target genes and thus result in a neurodevelopmental disorder." (PMID 34573379, 2021). "The fact that mutations in KDM5A, KDM5B, and KDM5C all cause neurodevelopmental disorders, indicates that their function in the brain is nonredundant." (PMID 33350388, 2020).
adenocarcinoma (1 paper, 2023). A common cancer characterized by the presence of malignant glandular cells. "We utilized immunohistochemistry to examine KDM5B protein expression in two PCa cohorts that contained benign prostate tissue, primary adenocarcinoma, metastatic and neuroendocrine prostate specimens." (PMID 37152294, 2023). "None of the cases had copy number alterations and only two cases possessed a KDM5B coding variant, suggesting KDM5B changes at the transcriptional level in adenocarcinomas are not attributable to sequence or copy number alterations." (PMID 37152294, 2023).
bacterial infection (1 paper, 2020). "The four CHIA, CHI3L2, PRDM2 and KDM5B genes that we identified on BTA4 and 16 in the Swedish Red Cattle were previously reported as disease resistance genes (i.e. to gastrointestinal nematodes or bacterial infection) in independent studies on sheep and cattle breeds." (PMID 32887549, 2020).
infectious disease (1 paper, 2022). A disorder directly resulting from the presence and activity of a microbial, viral, or parasitic agent in humans. "For the important histone H3K4me2/3 demethylase KDM5B, previous studies on its function have focused on oncological and infectious diseases." (PMID 36481938, 2022).
KDM5B also shares sentences with these, for which no sentence is quoted: acute myeloid leukemia (4 papers); esophageal cancer (4); ductal breast adenocarcinomas (3); hypopharyngeal squamous cell carcinoma (3); lymph node metastasis (3); uveal melanoma (3); colon cancer (2); congenital heart disease (2); medulloblastoma (2); nasopharyngeal carcinoma (2); neurological diseases (2); pancreatic ductal adenocarcinoma (2); Stomach Adenocarcinoma (2); thymoma (2); adenoma (1); Anxiety (1); astrocytoma (1); autoimmune disease (1); benign ovarian tumor (1); bladder urothelial carcinoma (1); brain cancer (1); Camptodactyly (1); Candida infections (1); Candidemia (1); cardiovascular diseases (1); cholangiocarcinoma (1); chronic pancreatitis (1); Cirrhosis (1); cutaneous melanoma (1); epileptic syndrome (1).
A further 26 diseases each share a sentence with KDM5B in 1 paper.